WT1 (WT1 transcription factor)
Diseases named in the same sentence as WT1 in open-access papers (continued):
Sharing a sentence is not in itself a finding about the gene and the disease.
myocardial infarction (continued). "Myocardial infarction strongly up-regulated Wt1-expressing cardiomyocytes, as well as individual nuclear Wt1 expression in cardiomyocytes." (PMID 34299295, 2021). "Our group was the first to demonstrate that Wt1 is a useful early marker of myocardial infarction, a finding later confirmed by others." (PMID 34299295, 2021). "Tang and colleagues reported an up- regulation of Wt1 expression in the pericardial adipose tissue following myocardial infarction." (PMID 34299295, 2021). "In the adult, Wt1 was reactivated in cardiomyocytes 48 h and 3 weeks following myocardial infarction." (PMID 33919406, 2021). "Wilms’ tumor 1 (Wt1) is a regulatory gene of epicardium‐derived cells that contributes to cardiovascular cell types and is activated in adult epicardium after myocardial infarction." (PMID 32096563, 2020). "Lineage tracing with Wt1Cre mouse showed that Wt1+ epicardial cells differentiated into cardiomyocyte after myocardial infarction." (PMID 31269439, 2019). "In a mouse model of myocardial infarction, WT1 is upregulated in the coronary vasculature downstream of ligated coronary arteries, and this regulation is dependent on a hypoxia-response element (HRE) in the WT1 promoter." (PMID 25794157, 2015). "WT1 is upregulated by hypoxia in endothelial cells in a coronary artery ligation model of myocardial infarction, and WT1 expression has also been demonstrated in tumor endothelial cells." (PMID 24810959, 2014). "Taken together, these observations point to a Wt1-derived population of cells, that is capable of differentiating into the myocardial lineage after a myocardial infarction." (PMID 23028582, 2012). "The strong cardiomyocytic WT1 re-expression after myocardial infarction supports the idea that it could have a cardioprotective role." (PMID 39768169, 2024). "As WT1 seems to be implicated in cardiac calcium regulation, it might prevent cardiomyocytic Ca2+ intracellular accumulation, suggesting that WT1 might be involved in the reduction in the elevated levels of calcium after myocardial infarction." (PMID 39768169, 2024). "The role played by WT1 in the adult myocardium seems to be more important under pathophysiological conditions, and this could be related to the observation of an upregulation of WT1 expression in cardiomyocytes following myocardial infarction." (PMID 37233178, 2023). "However, in adults, WT1 is still involved in homeostasis processes for tissue maintenance and recovery, resulting in continuous WT1 expression in renal podocytes and temporary WT1 expression in epicardial cells after a myocardial infarct." (PMID 36816758, 2023). "We detected Wt1+ cardiomyocytes already 48 h after myocardial infarction." (PMID 34299295, 2021). "De novo cardiomyocytes were reported to develop in adjacent areas of a myocardial infarction and hypoxic regulation of Wt1 re-expression might also function to promote the tissue regeneration by cardiomyocytes differentiation from an activated progenitor pool." (PMID 33919406, 2021). "A function for Wt1 in cardiac repair and regeneration has been proposed based on the finding that it is strongly re-expressed in epicardial, endothelial, and myocardial cells after myocardial infarction." (PMID 34299295, 2021). "Without using Tβ4, the authors observed a significant increase of Wt1 expression and proliferation in the epicardium shortly after myocardial infarction, leading to the formation of a Wt1-lineage-positive subepicardial mesenchyme until two weeks post-infarction." (PMID 34299295, 2021). "As similar processes are employed during organ development and regeneration, we hypothesized that Wt1 might contribute directly to cardiomyocyte cellular and functional differentiation in adult hearts following myocardial infarction (MI)." (PMID 33919406, 2021). "Wt1 upregulation after myocardial infarction has already been reported several years ago." (PMID 33919406, 2021).
myocardial infarction (continued). "Thus, with chromatin remodeling complexes, C/EBP regulates Wt1 expression in the adult epicardium after myocardial infarction through the seven ECRs." (PMID 32096563, 2020). "The identification of WT1 as a transcription factor that is essential for repair mechanisms involving various cell types within the heart may potentially enable the future development of a coordinated repair process following myocardial infarction." (PMID 40585983, 2025). "In control hearts, only a few Wt1 positive cardiomyocytes were detected while the frequency was notably increased in acute MI samples especially in the border zone of the myocardial infarction, and more Wt1-positive cardiomyocytes, compared to controls, were still detected 3 weeks after MI." (PMID 33919406, 2021). "Notably, Raldh2 CR2 and Wt1 CR14 enhancers are also activated in adult mouse hearts in response to myocardial infarction (MI), suggesting that embryonic epicardial enhancers are reactivated to repurpose the developmental gene program in adult hearts after injury." (PMID 30583498, 2018). "In the epicardial cells, activation of the fetal reprograming process, characterized by the redeployment of WT1 expression, was dedicated to cardiac repair by cellular replacement and paracrine support for neoangiogenesis after myocardial infarction (MI)." (PMID 30103817, 2018). "To investigate the role of the epicardium in endogenous regeneration, we induced a myocardial infarction (MI) in mice in which the Wilm's Tumor 1 (Wt1)-lineage is genetically labeled." (PMID 23028582, 2012). "As such, there has been a research into synthetically inducing epicardial expression of WT1 and EMT-related genes as it presents an attractive stem cell-based therapy to enable cardiac repair post-myocardial infarction." (PMID 31752983, 2019). "In a mouse myocardial infarction model we analyzed the spatio-temporal changes in expression of embryonic epicardial, EMT, and stem cell markers and the contribution of cells of the Wt1-lineage to the infarcted area." (PMID 23028582, 2012). "Regarding a possible role of epicardial-derived Wt1 expressing progenitor cells for cardiac repair, the situation is comparable with some studies postulating an important role after myocardial infarction, while others did not confirm these results." (PMID 33919406, 2021).
glomerular disease (21 papers, 2012 to 2026). "Pathogenic variants in the WT1 gene lead to glomerulopathies, with a histopathological picture including focal and segmental glomerulosclerosis (FSGS) and diffuse mesangial sclerosis." (PMID 40332152, 2025). "FS, caused by a pathogenic variant in intron 9 of the WT1 gene, is characterized by progressive glomerulopathy, gonadoblastoma developing in the second decade of life, and complete gonadal dysgenesis (CGD) in 46,XY individuals." (PMID 40332152, 2025). "WT1 mutations affecting the second to third zinc finger motifs (residue 428–511) often lead to infantile-onset glomerulopathy that progresses rapidly to end-stage renal failure by the age of 2.5 years." (PMID 41450889, 2025). "A variety of additional phenotypes have been linked to germline WT1 aberrations, including glomerulopathy, urogenital anomalies, and more rarely gonadoblastoma." (PMID 39698353, 2024). "The underlying mechanism of CKD in patients with WT1 variants is typically a progressive glomerulopathy." (PMID 39698353, 2024). "Patients with germline WT1 variants were typically identified by the presence of early-onset glomerulopathy, and WT1 testing was often limited to the hotspot region." (PMID 39698353, 2024). "This contributes to the paradigm that calls for the genetic investigation including karyotype of any phenotypic female who presents with CNS, SRNS or proteinuria, or ESKD concerning for possible 46XY sex reversal associated with WT1 glomerulopathy." (PMID 35498778, 2022). "Early recognition of WT1 mutation is essential for comprehensive surveillance of potential malignancy, avoidance of immunosuppressants for glomerulopathy, and establishing long-term multidisciplinary management." (PMID 35498778, 2022). "Among syndromic forms, WT1-associated glomerulopathy is the most frequent, followed by Pierson syndrome caused by LAMB2 biallelic pathogenic variants." (PMID 32467597, 2020). "In small clinical studies and collections of patient cases with kidney diseases including WT1 mutation-associated glomerular disease, membranous nephropathy, and Alport nephropathy, CsA or FK506 can improve the course of the kidney disease." (PMID 33604334, 2020). "NPHS2-related SRNS and WT1-associated glomerulopathy are the two forms of the disease with the most significant intra- and inter-family variability, with age-dependent penetrance reflecting defective variant type." (PMID 32467597, 2020). "4-PBA treatment resulted in decreased tubular lesions, interstitial fibrosis and tubular apoptosis in WT1+/mut mice which develop glomerular disease due to a mutation in WT1, an important regulator of podocyte function." (PMID 28148966, 2017). "Nephrin, podocin, synaptopodin, podocalyxin, CD2AP, ACTN4 (encodes for α-actinin 4), PTPRO (encodes for GLEPP-1), and WT1 mRNA have been isolated from urine of patients with varying glomerulopathies." (PMID 24327929, 2013). "Karyotype–phenotype and associated Wilms and gonadal tumors in WT1 glomerulopathy." (PMID 35498778, 2022). "Exosomes containing WT1 and podocalyxin have been identified in urinary supernatants of various human glomerular diseases and animal models by western blotting and podocyte-specific mRNAs." (PMID 38402504, 2024). "There were 324 subjects extracted from the literature review and 9 from our case series for a total of 333 cases of WT1 glomerulopathy." (PMID 35498778, 2022). "However, in different experimental models of mice and rats with glomerular disease, increased glomerular desmin staining is recognized as a marker of podocyte dedifferentiation and injury and is followed by decreased nuclear WT1 expression and loss of slit diaphragm proteins." (PMID 32982795, 2020). "We conclude that these data support a role for Notch activation in human WT1-mediated glomerular disease." (PMID 29398135, 2018). "Together, these data suggest that post-translational modification of Notch components are active in early Wt1 glomerulopathy." (PMID 29398135, 2018).
glomerular disease (continued). "Conditional inactivation of Notch1 and its transcriptional targets in both early and late stages of Wt1 glomerulopathy would further define the role and window for Notch activation in disease pathogenesis." (PMID 29398135, 2018). "Following our observation of Notch activation in murine Wt1 glomerulopathy, we next tested biopsy samples from a human subject with FSGS associated with the WT1 c.1390G>T mutation." (PMID 29398135, 2018). "We conclude that genetic rescue of Wt1 glomerulopathy by Notch inhibition would be best validated with in vivo strategies." (PMID 29398135, 2018). "Using an inducible model of Wt1 deletion, we demonstrate a role for Notch activation in the pathogenesis of Wt1 glomerulopathy." (PMID 29398135, 2018). "Compiled data on age of onset, presentation, and complications in WT1 glomerulopathy." (PMID 35498778, 2022). "In this contest, we hypothesized a normalizing role by WT1, as an alternative and in combination with that of other genes, previously accepted to normalize podocytes expression in glomerular diseases." (PMID 34441433, 2021). "We recommend individuals with WT1-glomerulopathy to be evaluated for urogenital malformations." (PMID 32467597, 2020). "Following our observation of increased podocyte apoptosis in CAGG-CreERTM+/−;Wt1f/f transgenic mice, we hypothesized that podocyte Notch activation plays a role in early Wt1 glomerulopathy." (PMID 29398135, 2018). "Data from one study presented that podocyte specific urinary exosomes could be quantified from patients and animal models of glomerulopathies: the podocyte specific aspect of these exosomes as being the transcription factor WT1." (PMID 24327929, 2013). "Thus, with the given data, urinary exosomal WT1 is specific for a diagnosis of glomerulopathy; however, more work will have to be done to elaborate on the usefulness of urinary exosomal WT1 as a biomarker of podocyte injury." (PMID 24327929, 2013). "In addition, WT1 is downregulated in a variety of glomerular diseases with podocyte injury, and WT1 mRNA is detected in the urine of some patients with glomerular diseases." (PMID 22693670, 2012). "We hypothesize that podocyte Notch activation plays a role in early Wt1 glomerulopathy." (PMID 29398135, 2018). "It should be noted that while WT1 is a proven histologic biomarker of podocytes, in a number of glomerulopathies WT1 protein is immunohistochemically expressed in glomerular parietal epithelium; therefore, WT1 as a biomarker of podocytes may not be exclusive and specific in diseased states." (PMID 24327929, 2013). "Mutations in the genes that code for proteins that are expressed in podocytes including nephrin, podocin, WT1, α-actinin-4, inverted formin 2 (INF2), TrpC6, MYH9, and phospholipase Cε1, lead to glomerular disease." (PMID 27942003, 2016). "Of 76 articles identified with keywords, 43 were excluded due to the lack of WT1 glomerulopathy cases, the lack of clinical data on sex/karyotype, age at presentation, or duplicated database." (PMID 35498778, 2022). "This prominent induction of miR-92a was further demonstrated in WT1-expressing podocytes in kidney biopsies from individuals diagnosed with crescentic RPGN but not in those patients with non-proliferative glomerulopathies such as membranous nephropathy." (PMID 29184126, 2017).
multiple myeloma (21 papers, 2007 to 2024). "In the phase I clinical trial, autologous Langerhans-type DCs were electroporated with mRNA molecules encoding Cancer testis antigen 7 (CT7), Melanoma-associated antigen (MAGE) A3, and Wilms tumor 1 (WT1) and administered intradermally into patients with multiple myeloma following ASCT." (PMID 39696625, 2024). "Donor-derived cytotoxic T-lymphocytes directed against myeloma-associated antigens such as Wilms tumor 1 (WT1) or other cancer testis antigens may enable a GVM effect without GVHD." (PMID 29322027, 2017). "Despite that, myeloma cells were found to be highly sensitive to lysis by WT1-specific cytotoxic T lymphocytes." (PMID 36760714, 2023). "Autologous Langerhans-type dendritic cells (LCs) electroporated with mRNAs encoding CTA 7 (CT7), MAGE-A3, and Wilms tumor 1 (WT1) increase the number of antigen -specific CD4+ T cells and CD8+T cells in patients with multiple myelomas (MM)." (PMID 37834126, 2023). "WT-1 is a suitable target for adoptive immunotherapy being differentially expressed in over 70% of AMLs and myelomas and being also expressed at high levels in advanced MDS." (PMID 28635677, 2017). "However, WT1 protein expression and its clinical correlation in multiple myeloma (MM) patients are still limited." (PMID 36760714, 2023). "We analyzed the use of the HLA*A2:01-positive multiple myeloma cell line U266 as a tool for the rapid assessment of HLA-A2-restricted WT1-specific T-cell responses following electroporation with full-length WT1 mRNA, in comparison with WT1 peptide loading." (PMID 31972992, 2020). "Importantly, in transplant recipients treated with unselected donor lymphocytes for the relapse of AML or myeloma, expansion of WT-1 specific T-cells closely correlates with the eradication of tumour cells and the achievement of complete remission." (PMID 28635677, 2017). "While WT1 is also frequently expressed, albeit at lower level, in lymphoid malignancies, myeloma cells may be efficiently recognized and lysed by WT1-specific CTL." (PMID 22649466, 2012). "Popular targets have included myeloma patient-specific idiotypic immunoglobulin as well as a number of cancer testis antigens such as MAGE-C1, NY-ESO-1, MUC-1, and WT-1." (PMID 32327728, 2020).
acute lymphoblastic leukemia (19 papers, 2006 to 2025). Leukemia with an acute onset, characterized by the presence of lymphoblasts in the bone marrow and the peripheral blood. "Here, we show the tropism and selectivity exhibited by Wt1-5 for Reh cells, a human acute lymphoblastic leukemia cell line, that have a higher expression of the cell surface Hsp90, Hsp70, Hsc70, PDI and αVβ3 as compared with their very low or absent expression in PBMCs." (PMID 32722005, 2020). "The prognostic role of Wilms’ tumor 1 (WT1) gene expression at diagnosis in children with B cell precursor acute lymphoblastic leukemia (BCP-ALL) is still controversial." (PMID 38293695, 2023). "WT1 mutations have been found in about 10%-15% of cases of AML and 20% of cases of biphenotypic leukemia, but mutations are rare in acute lymphoblastic leukemia (ALL)." (PMID 25035671, 2014). "The present results allow us to conclude that rotavirus Wt1-5 can be a potential candidate to be further studied as an oncolytic agent that can use cell surface proteins Hsp90, Hsp70, Hsc70, PDI, and integrin β3 to infect human acute lymphoblastic leukemia cells expressing these cellular proteins." (PMID 32722005, 2020).
diabetic nephropathy (19 papers, 2012 to 2025). "Since the reduction in podocyte number and density has been linked to proteinuria and progression of diabetic nephropathy, WT1, as a marker to evaluate podocyte damage, has been a major focus of the diabetic nephropathy biomarker investigations." (PMID 23544132, 2013). "In this regard loss of podocyte markers including WT1 has been reported in renal biopsy tissue in diabetic nephropathy." (PMID 23544132, 2013). "On the other hand, the role of WT-1/EZH2/β-catenin was earlier confirmed with regard to podocyte integrity in a diabetic nephropathy model." (PMID 41282610, 2025). "Consistently, Wan’s research demonstrates that a decrease of EZH2 is beneficial for podocyte injury by antagonizing Wilm’s tumor 1 (WT1) in diabetic nephropathy." (PMID 32508971, 2020). "Additionally, previous studies show crosstalk between WT-1 and β-catenin as a protective element of podocyte against diabetic nephropathy via the repression of EZH2/β-catenin." (PMID 41282610, 2025). "And transcription factors HIF1α, KLF4, KLF5, RUNX1, SP1, VDR, WT1 may be also related to diabetic nephropathy." (PMID 34735495, 2021). "Transcription factors HIF1α, KLF4, KLF5, RUNX1, SP1, VDR and WT1 may be related to diabetic nephropathy." (PMID 34735495, 2021). "The same marker was also explored in patients with diabetic kidney disease where WT1 expression in urinary exosomes was significantly higher in patients with proteinuria than those without and in patients with FSGS where an association with the activity of the disease was shown." (PMID 25310591, 2014). "Time-dependent study revealed that podocin and WT1 expression was down-regulated as early as 6 hours' incubation, consistent with the clinical manifestation that podocyte injury is one of the initial events during diabetic nephropathy." (PMID 22848482, 2012). "The predominant presence of WT1 protein in urinary exosomes of diabetic patients and increase in its expression level with decline in renal function suggest that it could be useful as early non-invasive marker for diabetic nephropathy." (PMID 23544132, 2013). "WT-1 mRNA is generally not detected in the urine of MCD patients, but it is isolated in cases of diabetic nephropathy." (PMID 32849923, 2020).